PLCE1 (phospholipase C epsilon 1)
Diseases named in the same sentence as PLCE1 in open-access papers (continued):
Sharing a sentence is not in itself a finding about the gene and the disease.
congenital nephrotic syndrome (5 papers, 2009 to 2024). "PLCE1 mutations have been shown to result in familial nephrotic syndrome suggesting that such interactions may be crucial in cell adhesion and reorganization as well as maintaining the structural integrity of the actin cytoskeleton." (PMID 19652713, 2009). "Most of the genes commonly associated with congenital nephrotic syndrome have reported ocular manifestations (NPHS1, NPHS2, WT1, LAMB2, PAX2, PLCE1)." (PMID 37578539, 2024).
non-small cell lung carcinoma (5 papers, 2015 to 2023). A group of at least three distinct histological types of lung cancer, including non-small cell squamous cell carcinoma, adenocarcinoma, and large cell carcinoma. "As a direct target of certain miRNAs, PLCE1 is involved in regulating the metastasis and growth of esophageal tumor and non-small cell lung cancer." (PMID 35765945, 2022). "It was suggested that miR-1976 could function as a tumor suppressor that regulates PLCE1 in non-small cell lung cancer." (PMID 37189754, 2023).
skin cancer (5 papers, 2012 to 2021). "Although PLCE1 expression has been found to promote tumor formation in a mouse model of skin cancer, PLCE1−/− mice have exhibited decreased susceptibility to tumor development." (PMID 29190930, 2017). "Previous findings demonstrated a significant reduction in PLCE1 expression in Ras-driven cancers, such as colorectal, lung, and skin tumors; as such, PLCE1 functions as a tumor-suppressor gene." (PMID 26657507, 2016). "Besides ESCC, PLCE1 was identified as an oncogene in skin cancer, gallbladder cancer and prostate cancer." (PMID 34412652, 2021). "Recent studies also have shown that PLCE1 could play crucial roles in intestinal tumorigenesis and skin tumor formation." (PMID 22412849, 2012).
squamous cell carcinoma (5 papers, 2011 to 2022). A carcinoma arising from squamous epithelial cells. "Many studies have found that PLCE1 gene polymorphism not only regulates cell growth, differentiation, apoptosis, and angiogenesis but also increases the susceptibility to esophageal, gastric, colon cancer, and squamous cell carcinoma of the head and neck." (PMID 35765945, 2022). "In the present work, we showed that the expression of PLCE1 was increased in Barrett's esophagus and inflammatory squamous epithelia, and significantly increased in esophageal adenocarcinoma and squamous cell carcinoma." (PMID 28402280, 2017). "These suggested, together with the results of rs3765524 genotyping by stratified analysis, that PLCE1 protein may be involved in carcinogenesis of NCC and adenocarcinoma, although more significant association has been found with EC, CC, and squamous carcinoma." (PMID 30931333, 2019).
colon cancer (4 papers, 2011 to 2022). "Reduced levels of PLCE1 proteins are present in colon cancer." (PMID 29190930, 2017). "Our results from qMSP and bisulfite sequencing cannot confirm PLCE1 as a target for this type of epigenetic silencing, and despite high frequency of methylation in colon cancer cell lines, methylation in the PLCD1 promoter can only explain reduced expression in a subgroup of the carcinomas." (PMID 21909432, 2011). "Further, it was recently reported that overexpression of PLCE1 in a colon cancer cell line inhibited tumor cell proliferation, reduced number of colonies formed, reduced migration, and increased apoptosis, suggesting a tumor suppressive role for this gene in CRC." (PMID 21909432, 2011). "For PLCE1, only one of 19 colon cancer cell lines showed promoter methylation." (PMID 21909432, 2011). "Upregulation of IFITM3 and downregulation of Period 3 (PER3) and phospholipase C epsilon 1 (PLCE1) were subsequently validated, and roles for each in colon cancer development have been proposed." (PMID 26992238, 2016).
hepatocellular carcinoma (4 papers, 2017 to 2025). A malignant tumor that arises from hepatocytes. "As to hepatocellular carcinoma, the upregulation of PLCE1 could be caused by virus-stimulated inflammation because most hepatocellular carcinomas are linked to hepatitis virus." (PMID 28402280, 2017). "This reduction aligns with findings in hepatocellular carcinoma tissue and cell lines, where the expression and protein levels of PLCE1 were significantly lower in cancer." (PMID 40819340, 2025). "PLCE1 was identified to mediate diverse external signals and has been reported to correlate with tumor clinical stages and survival, including hepatocellular carcinoma, colorectal, bladder, gastric, head and neck, and gallbladder cancers." (PMID 30609930, 2019). "In hepatocellular carcinoma, PLCE1 was significantly increased from 0.62 ± 0.15 in normal (n = 220) to 0.78 ± 0.34 in hepatocellular carcinoma (n = 225), and PRKCA was increased from 4.90 ± 1.46 in normal to 7.13 ± 4.22 in hepatocellular carcinoma." (PMID 28402280, 2017). "The present study investigated the prognostic significance of PLCE1 gene polymorphisms and expression combined with serum α-fetoprotein (AFP) level in hepatitis B virus (HBV)-related hepatocellular carcinoma (HCC)." (PMID 28418898, 2017).
migraine (4 papers, 2020 to 2023). "PLCE1 and NMUR2, whose variants showed noteworthy association with migraine susceptibility, were found to be involved in two pathways called “positive regulation of cytosolic calcium ion concentration” and “inositol phosphate-mediated signaling” detected in our study." (PMID 32046629, 2020).
breast carcinoma (3 papers, 2013 to 2020). "Furthermore, research based on the non-DTCs (such as hepatic cellular cancer, lung cancer, breast cancer etc.)should be performed to explore the association between PLCE1 gene polymorphisms and cancer risks." (PMID 24116107, 2013).
cardia (3 papers, 2012 to 2015). "Compared with adjacent normal tissues, three examined gastric tumors displayed up-regulation of PLCε1 expression at both mRNA and protein levels, but all of severe atrophic gastritis tissues had lower expression of PLCε1." (PMID 23077637, 2012). "Here, our study firstly demonstrated that PLCε1 was up-regulated in human gastric tumor tissues, but was down-regulated in inflammation environment, compared with normal tissues." (PMID 23077637, 2012).
glioblastoma (3 papers, 2017 to 2020). The most malignant astrocytic tumor (WHO grade IV). "In brain glioblastoma, PLCE1 was increased from 1.17 ± 0.06 in normal (n = 4) to 3.18 ± 1.28 in glioblastoma (n = 80), and PRKCA was increased from 1.73 ± 0.23 (n = 4) in normal to 2.11 ± 0.44 in glioblastoma (n = 80)." (PMID 28402280, 2017).
lung carcinoma (3 papers, 2013 to 2025). "For instance, PLCε-1 promotes lung cancer growth by modulating apoptosis and influences prostate cancer through mitochondrial oxidative metabolism." (PMID 40519297, 2025).
adenoma (2 papers, 2019 to 2025). A neoplasm arising from the epithelium. "VEGF-A, as an angiogenic switch, occurs at the early stage of tumorigenesis around low-grade adenoma formation in PLCE1−/− mice." (PMID 30609930, 2019).
atrophic gastritis (2 papers, 2012 to 2019). "The immunohistochemical results showed that PLCε1 expression was positive in 275 (37.0%) atrophic gastritis including 106 (37.7%) mild atrophic gastritis, 98 (26.0%) moderate atrophic gastritis and 71 (28.1%) in severe atrophic, respectively." (PMID 23077637, 2012). "Thirdly, an independence immunohistochemical analysis of 799 chronic atrophic gastritis tissue specimens demonstrated that PLCε1 expression in atrophic gastritis tissues were down-regulated since PLCε1 expression was negative in 524 (65.6%) atrophic gastritis." (PMID 23077637, 2012). "In agreement with the results of immunohistochemical tissue microarray analysis, the paired analysis also showed PLCε1 was over-expressed in tumor, but down-regulated in severe atrophic gastritis in comparison with the matched adjacent normal tissues." (PMID 23077637, 2012). "Previously, we conducted a comprehensive analysis of PLCE1 expression in atrophic gastritis and GC tissues, which revealed that differential expression of PLCE1 may distinguish GC from inflammation lesions." (PMID 30931333, 2019). "Therefore, compared with tumor and normal tissues, atrophic gastritis samples had decreased PLCε1 expression (p<0.001)." (PMID 23077637, 2012). "Moreover, in severe atrophic gastritis tissues, 6 (2.37%) samples showed positive PLCε1 expression in inflammatory cells or lymphatic tissues." (PMID 23077637, 2012). "To determine PLCε1 expression in inflammation environment, we extended PLCε1 immunohistochemical analysis using another independent set of paraffin-embedded tissue sections of 799 atrophic gastritis tissue specimens." (PMID 23077637, 2012). "Moreover, in our work, PLCε1 protein can be detected in inflammatory cells and lymphocyte tissues in some adjacent normal tissues at N0 degree and some severe atrophic gastritis tissues." (PMID 23077637, 2012).
Barrett esophagus (2 papers, 2017 to 2019). Esophageal lesion lined with columnar metaplastic epithelium which is flat or villiform. "The results showed that rs4072037 SNP in PLCE1 is associated with higher risk of upper gastrointestinal cancer, while rs2274223 and rs4072037 were correlated with increased risk of esophageal adenocarcinoma." (PMID 31649800, 2019). "Interestingly, PRKCA was also altered with the changes of PLCE1, suggesting the important significance of their correlation in the development of esophagitis and Barrett's esophagus and their malignant transformation." (PMID 28402280, 2017). "To investigate the changes of PLCE1 and PRKCA in BE and EAC, we deeply mined the Kim's Oncomine data and found that both PLCE1 and PRKCA mRNA levels were dramatically increased in Barrett's Esophagus and EAC, in comparison with the non-tumor esophageal mucosa." (PMID 28402280, 2017).
cardia gastric cancer (2 papers, 2012 to 2013). "This meta-analysis found that the PLCE1 rs2274223 gene variant was linked to greater susceptibility for gastric cardia cancer." (PMID 23826241, 2013). "In a subgroup analysis, the PLCE1 rs2274223 polymorphism was found to be a very sensitive marker for gastric cardia cancer as shown by the homozygous genetic model (OR = 2.23), heterozygous genetic model(OR = 1.59) and allelic genetic model (OR = 1.47)." (PMID 23826241, 2013). "So in this article we also made a stratified analysis and found that PLCE1 polymorphism is significantly associated with gastric cardia cancer but not with gastric non-cardia cancer." (PMID 23826241, 2013).
cardiac hypertrophy (2 papers, 2016 to 2023). "Therefore, we focused on deciphering and discussing their regulatory roles in cardiac hypertrophy in the following sections and 5 focused NFAT associated genes (PLCE1, PPP3R1, PPP3CB, CAMK1, MEF2C) were studies for experimental validation." (PMID 27907007, 2016). "Notably, the expression patterns of PPP3CB, PPP3R1, PLCE1, MEF2C and CAMK1 in the “NFAT in cardiac hypertrophy” pathway played a significant role in the activation of hypertrophy of atrial myocytes in MR patients compared to normal subjects." (PMID 27907007, 2016).
focal glomerulosclerosis (2 papers, 2010 to 2020). "Nevertheless, there is wide overlap between different forms and cases of uncommon associations, such as the presence of diffuse mesangial sclerosis in patients with NPHS2 mutations or focal glomerulosclerosis in patients with variants in the PLCE1 gene." (PMID 19066979, 2010).
gastric adenocarcinoma (2 papers, 2012 to 2019). "In this study, we attempted to evaluate the correlation between the PLCE1 (rs2274223 A>G) polymorphism and the risk of gastric adenocarcinoma in northern Iran." (PMID 31649800, 2019). "In this case-control study, we considered the correlation between a potentially functional SNP of PLCE1 (rs2274223) and the risk of gastric adenocarcinoma in Iranian population." (PMID 31649800, 2019). "Recent genome-wide association studies (GWAS) have found a single nucleotide polymorphism (SNP, rs2274223 A>G) in PLCE1 to be associated with risk of gastric adenocarcinoma." (PMID 22412849, 2012). "We further measured the PLCE1 mRNA expressions in paired tissue samples of different genotypes to investigate the possibly functional role of variant rs2274223 in the etiology of gastric adenocarcinoma." (PMID 22412849, 2012). "Recently, two genome-wide association studies (GWASs) have reported a shared susceptible locus at 10q23 (rs2274223A>G, exon 26) in the PLCE1 gene associated with risk of gastric adenocarcinoma." (PMID 22412849, 2012). "Our results further confirmed that genetic variations in PLCE1 may contribute to gastric adenocarcinoma risk in an eastern Chinese population." (PMID 22412849, 2012).
glaucoma (2 papers, 2018). Increased pressure in the eyeball due to obstruction of the outflow of aqueous humor. "These included Angpt1, Ank, Cadm2, Fmnl2, Plce1, Thsd7a, and Tmtc2 at the novel POAG/glaucoma loci identified in the current study." (PMID 29891935, 2018).
glioma (2 papers, 2018 to 2024). A benign or malignant brain and spinal cord tumor that arises from glial cells (astrocytes, oligodendrocytes, ependymal cells). "Furthermore, we found that six downregulated genes, including pLCE1, PRPS2, FH, ASL, DTYMK, and CTPS1 were significantly increased in high-grade glioma tissues (p < 0.001)." (PMID 38438374, 2024).
glomerulosclerosis (2 papers, 2015 to 2024). A hardening of the kidney glomerulus caused by scarring of the blood vessels. "Compared with wild-type littermates, HBP increased proteinuria by 20 times and glomerulosclerosis significantly in PLCE1 deficient mice." (PMID 38390575, 2024).
head and neck squamous cell carcinoma (2 papers, 2011 to 2020). A squamous cell carcinoma that arises from any of the following anatomic sites: lip and oral cavity, nasal cavity, paranasal sinuses, pharynx, larynx, and salivary glands. "Phospholipase C epsilon 1 (PLCE1) (an effector of Ras) belonging to the phospholipase family plays crucial roles in carcinogenesis and progression of several cancers, including squamous cell carcinoma of the head and neck (SCCHN)." (PMID 21689432, 2011).
kidney failure (2 papers, 2016 to 2025). An acute or chronic condition that is characterized by the inability of the kidneys to adequately filter the blood. "PLCE1 truncating mutations generally lead to early-onset proteinuria and rapid progression to kidney failure, whereas missense mutations are linked to later-onset disease with a slower course." (PMID 41368354, 2025).
lymph node metastasis (2 papers, 2020 to 2021). "Reduced PLCE1 mRNA expression was related to lymph node metastasis (P = .02), distant metastasis (P = .03), TNM tumour stage (P = .02) and lymphovascular invasion (P = .04)." (PMID 34173324, 2021).
melanoma (2 papers, 2016 to 2018). A malignant, usually aggressive tumor composed of atypical, neoplastic melanocytes. "NDC80, PLCE1 and AKAP13 have so far not been studied in melanoma." (PMID 27853253, 2016).
nephrotic syndrome, type 3 (2 papers, 2017 to 2022). "The top significant variant (NM_016341.4:c.4724G>C) is a missense variant within the PLCE1 gene that results in the substitution of arginine for proline at position 1,575 (p.R1575P) and is classified by ClinVar as uncertain significance for association with nephrotic syndrome type 3." (PMID 36035137, 2022). "When the same variant was not reported before for association with nephrotic syndrome type 3, several other variants within PLCE1 have been reported in familial and sporadic variants within PLCE1." (PMID 36035137, 2022).
osteosarcoma (2 papers, 2022 to 2023). A usually aggressive malignant bone-forming mesenchymal neoplasm, predominantly affecting adolescents and young adults. "In addition, PLCE1 may induce immune escape in osteosarcoma through the CD70-CD27 signaling pathway." (PMID 37732314, 2023). "However, the biological role of PLCE1 in osteosarcoma (OS) is still poorly understood." (PMID 35765945, 2022).
renal carcinoma (2 papers, 2017 to 2022). A carcinoma arising from the epithelium of the renal parenchyma or the renal pelvis. "Studies have revealed that mutations in the PLCE1 gene or changes in PLCE1 expression are closely related to the susceptibility to a variety of tumors, such as gastric, colorectal, and renal cancer." (PMID 35765945, 2022). "The significant increase of PLCE1 and PRKCA was also observed in renal cancer and Yolk Sac Seminoma." (PMID 28402280, 2017).
aortic aneurysm (1 paper, 2025). A ruptured aneurysm located in the wall of the proximal portion of the descending aorta proceeding from the arch of the aorta. "However, the candidate SNP in this locus, rs10882399, was found to be in proximity to the gene PLCE1, which overlaps with the 3′UTR of NOC3L and has been implicated in the development of aortic aneurysm and dissection." (PMID 41251448, 2025).
aortic valve disease (1 paper, 2016). "In this study, PLCE1 was found to be up-regulated in MR patients compared to patients with aortic valve disease and normal subjects." (PMID 27907007, 2016).
atrial septal defect (1 paper, 2014). Interauricular communication is a congenital malformation characterized by a communication between the atrial chambers of the heart. "The child with the homozygous PLCE1 mutation also had an atrial septal defect and right atrial thrombectomy." (PMID 24902943, 2014).
cervical (1 paper, 2017). "For instance, PLCE1 was significantly increased from 0.14 ± 0.06 in normal cervix (n = 10) to 0.41 ± 0.11 in cervical high grade introepithelial neoplasm (HGN, n = 7) and 0.37 ± 0.15 in cervical squamous cell carcinoma (n = 21)." (PMID 28402280, 2017).
cervix cancer (1 paper, 2015). "Genes PFDN4, CASP1, PLCE1, ICOSLG, GADD45G, SMARCA2, and TSPO are located in different chromosomes, and there are reports for changes in each one of these chromosomes in cervix cancer, for examples the reader is refer to:." (PMID 26388997, 2015).
Cirrhosis (1 paper, 2017). A chronic disorder of the liver in which liver tissue becomes scarred and is partially replaced by regenerative nodules and fibrotic tissue resulting in loss of liver function. "The stratified analysis also revealed that high PLCE1 expression increased the risk of recurrence and death in patients who were male and had early-stage BCLC, a single tumor, cirrhosis, and AFP level > 300 ng/ml." (PMID 28418898, 2017). "In the stratified analysis, high PLCE1 expression increased the risk of recurrence and death among patients who were male and had early-stage BCLC, who had a single tumor, cirrhosis, AFP level > 300 ng/ml." (PMID 28418898, 2017).
Cluster headache (1 paper, 2025). A type of headache characterized by repeated attacks of unilateral pain lasting 15 to 180 minutes and associated with local autonomic signs. "Lastly, they expanded their analysis to include ANO3, ITGAL, PLCE1, and PCDHB6 genes and found rs1531394 in the ANO3 gene to be significantly associated with cluster headache." (PMID 39560176, 2025).